TRPM5 (transient receptor potential cation channel subfamily M member 5)
Diseases named in the same sentence as TRPM5 in open-access papers (continued):
Sharing a sentence is not in itself a finding about the gene and the disease.
influenza (2 papers, 2022 to 2024). An acute viral infection of the respiratory tract, occurring in isolated cases, in epidemics, or in pandemics; it is caused by serologically different strains of viruses (influenzaviruses) designated A, B, and C, has a 3-day incubation period, and usually lasts for 3 to 10 days. "(A) Single-cell RNA-Seq UMAP clustering of sorted tuft cells (Epcam+Trpm5-GFP+) from Trpm5-GFP reporter mice at day 28 post influenza." (PMID 36073526, 2022). "(A) Representative immunostaining of lung sections from Trpm5-GFP reporter mice at day 35 post-influenza." (PMID 36073526, 2022). "DCLK1+TRPM5+ SCCs develop in the distal lung after severe influenza injury." (PMID 38061015, 2024). "Epcam+ Trpm5-GFP+ cells are bona fide tuft cells in the lung post-influenza." (PMID 36073526, 2022). "After influenza infection, DCLK1+TRPM5+ SCCs coexpress p63 and arise near Krt5+ cells, suggesting a common origin with p63+Krt5+ distal airway epithelial cells implicated in lung regeneration." (PMID 38061015, 2024). "We found that in Pou2f3-/-, Trpm5-/-, and Il4ra-/- animals, the percent of Agr2+ area within Krt5+ area was not significantly different from controls following influenza infection." (PMID 36073526, 2022).
leukemia (2 papers, 2021 to 2024). A malignant (clonal) hematologic disorder, involving hematopoietic stem cells and characterized by the presence of primitive or atypical myeloid or lymphoid cells in the bone marrow and the blood. "In a hospital-based case-control study on nucleotide polymorphisms in childhood leukemia, it was observed that patients with the CG or GG genotype of the rs2301696 location in TRPM5 had a decreased risk of developing childhood leukemia, compared to those with the CC genotype." (PMID 36046118, 2021).
parasite infection (2 papers, 2018 to 2021). "In the gastrointestinal tract, TRPM5-expressng tuft cells release the cytokine interleukin-25 to initiate type 2 immunity against parasite infection." (PMID 29615870, 2018).
viral infection (2 papers, 2021 to 2022). "Specialized chemosensory epithelial cells that express the transient receptor potential cation channel subfamily M member 5 (TRPM5) are found throughout the airways and intestinal epithelium and are involved in responses to viral infection." (PMID 33781205, 2021). "Our study provides new insights into a potential role for TRPM5-expressing cells in viral infection of the main olfactory epithelium." (PMID 33781205, 2021). "Our study provides new insights into a potential role for TRPM5-expressing microvillous cells in viral infection of the olfactory epithelium." (PMID 33781205, 2021). "We find profuse expression of transcripts involved in inflammation, immunity and viral infection in TRPM5-expressing microvillous cells compared to olfactory sensory neurons." (PMID 33781205, 2021). "(C) Whole lung airway resistance improves in Trpm5-/- mice following viral infection." (PMID 36129169, 2022). "To assess whether Trpm5-/- mice exhibited improved pulmonary mechanics after viral infection, we assessed airway resistance when challenged with increasing concentrations of methacholine." (PMID 36129169, 2022). "The number of tuft cells was reduced but not significantly following viral infection in the lung parenchyma of Trp63CreERT2;Trpm5-/-;R26Ai14 mice as compared to control mice (Trp63CreERT2;Trpm5+/-;R26Ai14) (P>0.05)." (PMID 36129169, 2022).
asthma (1 paper, 2022). "In most of the cells, TRP channels are expressed, and strong evidence for an essential role in airway function and associated diseases, such as CF, asthma, fibrosis and edema was demonstrated for TRPA1, TRPC6, TRPM2, TRPM5, TRPM7, TRPV2, TRPV4 and TRPV6." (PMID 36139480, 2022).
Chronic colitis (1 paper, 2021). A chronic inflammatory disease of the large intestine (colon, cecum and rectum). "Consistent with this, in the IL-10−/− chronic colitis model, Spry2 is elevated in colonic homogenates from adult animals with active inflammation versus young (pre-colitic) littermates, and these mice express reduced levels of tuft (Trpm5) and goblet cell (Muc2) markers in the distal colon." (PMID 33547321, 2021).
glaucoma (1 paper, 2013). Increased pressure in the eyeball due to obstruction of the outflow of aqueous humor. "In conclusion, this study demonstrated that a TRPM gene polymorphism is associated with POAG in the Turkish population, and the TRPM5 polymorphism also plays a role in the pathogenesis of this glaucoma." (PMID 24019741, 2013). "This is the first study showing a marked association between TRPM5 and glaucoma." (PMID 24019741, 2013). "TRPM5 channel localization in ocular tissue, physiologic function of this channel, and the contribution of this channel to the glaucoma pathogenesis are currently unknown, and require further studies." (PMID 24019741, 2013).
Glucose intolerance (1 paper, 2015). Glucose intolerance (GI) can be defined as dysglycemia that comprises both prediabetes and diabetes. "Together these observations suggest an important role for TRPM5 in diet induced glucose intolerance." (PMID 26397098, 2015). "This study point to an important role for the taste signalling system and TRPM5 in diet induced glucose intolerance." (PMID 26397098, 2015).
liver disease (1 paper, 2021). "In this setting, TRPM5 rs886277 polymorphism could lead to altered gene transcription in NK cells, contributing to liver disease’s pathogenesis." (PMID 33525598, 2021).
liver fibrosis (1 paper, 2021). "We also evaluated the association between TRPM5 rs886277 polymorphism and liver fibrosis progression by GLM tests." (PMID 33525598, 2021).
metabolic syndrome (1 paper, 2021). A cluster of metabolic risk factors for CARDIOVASCULAR DISEASES and TYPE 2 DIABETES MELLITUS. "Minor alleles of several TRPM5 SNPs, which are in linkage disequilibrium with rs886277, have been related to higher glucose level and reduced insulin sensitivity during an oral glucose tolerance test and metabolic syndrome." (PMID 33525598, 2021).
neurofibromatosis type 1 (1 paper, 2019). A clinically heterogeneous, neurocutaneous genetic disorder characterized by cafe-au-lait spots, iris Lisch nodules, axillary and inguinal freckling, and multiple neurofibromas. "Most significant enrichment was observed for NF1 (P = 0.000477, OR = 22.8), the gene causal for neurofibromatosis type 1 (NF1), followed by TRPM5, AP5B1, DNMT3L and ARFGEF1." (PMID 31175295, 2019).
ovarian carcinoma (1 paper, 2018). A malignant neoplasm originating from the surface ovarian epithelium. "Analysis of the frequently observed proteins by ANOVA confirmed increases in mean precursor intensity in ZFN91, TRPM5, SIRT1, CHD6, RIMS1, LOC101930455 (XP_005275896), CCDC37 and GIMAP4 between ovarian cancer versus normal female and other diseases or controls by the Tukey–Kramer HSD test." (PMID 30598658, 2018).
polyp (1 paper, 2022). A usually exophytic mass attached to the underlying tissue by a broad base or a thin stalk. "Healthy human sinus tuft cells resembled previous descriptions of human airway tuft cells, while canonical markers of mouse tuft cells such as TRPM5 and DCLK1 were present only in the allergic tuft cell population in polyp patients." (PMID 35608904, 2022).
rhinitis (1 paper, 2017). An inflammation of the mucous membrane lining the nose, usually associated with nasal discharge. "Chronic and severe chemical exposure is known to induce rhinitis, olfactory dysfunction, and other respiratory illnesses, which may be because such conditions likely overpower the ability of TRPM5-MCs to maintain MOE function." (PMID 28612045, 2017).
thymic carcinoma (1 paper, 2021). Thymic carcinoma (TC) is a type of thymic epithelial neoplasm characterized by a high malignant potential. "In addition, SOX9 expression was positively associated with the expressions of TRPM5, which is required for the function of thymic tuft cells, and KIT, which is frequently expressed in thymic carcinomas." (PMID 34778027, 2021).
thymoma (1 paper, 2021). A neoplasm arising from the epithelial cells of the thymus. "In addition, SOX9 expression was positively associated with POU2F3 and TRPM5 expressions, the master regulators of tuft cells, suggesting that high SOX9 expression might be associated with the tuft cell phenotype of thymomas." (PMID 34778027, 2021).
cancer (9 papers, 2011 to 2025). A tumor composed of atypical neoplastic, often pleomorphic cells that invade other tissues. "Although up-to-date knowledge regarding the relationship between cancer and TRPM5 is still poor, it has been linked to metabolic changes in the TME, potentially influencing tumor progression in metabolic disorders like diabetes-associated cancers." (PMID 40227837, 2025). "The altered expression profile of TRPM4 and TRPM5 has been associated with the etiology of several cancers." (PMID 32575381, 2020). "Literature citing a mechanism underlying the association of TRPM5 with cancer is scarce." (PMID 36046118, 2021). "One study examined the association of TRPM5 with patient survival in various cancers." (PMID 36046118, 2021). "Similarly, upregulated TRPM5 in several cancers including gastric cancer is linked to poor patient survival." (PMID 32575381, 2020). "The table highlights the roles of KATP, TRPM5, connexins, and pannexins in different types of cancer, their effects on tumor progression, and corresponding references." (PMID 40227837, 2025). "TRPM5, involved in intracellular calcium signaling and metabolic regulation, is often overexpressed in cancer cells, promoting their survival and proliferation." (PMID 40227837, 2025). "In silico analysis of TRPM5 mRNA levels in clinical samples from cancer patients were correlated with overall survival using an open database." (PMID 29108231, 2017). "TRPV1, TRPC1, TRPC6, and TRPM5 are also increased in cancer tissues, but further experiments are required to study the underlying mechanisms." (PMID 27023518, 2016). "Despite the lack of information regarding TRPM5 in cancer, its susceptibility to several stimuli such as pHe, temperature, and intracellular calcium, typical of the TME, makes it a possible target for cancer therapy." (PMID 40227837, 2025). "For example, the high intracellular calcium concentration resulting from TRPM5 activity enhances matrix metalloproteinase-9 (MMP-9) in tumors, which promotes ECM remodeling and contributes to cancer progression." (PMID 40507957, 2025). "The literature which does exist focuses on TRPM5-related mechanisms in the tumor microenvironment (TME), or in cancer metastasis." (PMID 36046118, 2021). "All tuft cell-like cancers identified in this way also strongly expressed other tuft cell-markers, such as TRPM5, SOX9, ASCL2, and AVIL but not CHAT." (PMID 36402755, 2022).
tumor (8 papers, 2017 to 2025). "We recently showed that TRPM5 is important for acidic pHe signaling and that high TRPM5 mRNA expression was associated with shorter survival of patients with some types of tumor." (PMID 31489536, 2020). "The results show that TRPV4, MCOLN1,and TRPM5 are expressed differently between normal and tumor tissues." (PMID 38188686, 2023). "TRPM5 only showed significant upregulation in OAC-tumor grades and metastatic stages in the OCCAMS dataset." (PMID 36046118, 2021). "On the other hand, we showed that constitutive expression of TRPM5 is apparently uninvolved in tumor growth in vivo." (PMID 29108231, 2017). "Treatment of tumor bearing mice with triphenylphosphine oxide (TPPO), an inhibitor of TRPM5, significantly reduced spontaneous lung metastasis." (PMID 29108231, 2017). "In our initial analysis, rare non-tumor cells clustered separately from tumor cells, and their identity was further validated by the expression of well-known stromal markers including Vim, Ptprc, Trpm5, Pecam1, Mgp, Cd79a, Itgam, Adgre1, Cd3g, and Marco." (PMID 33821796, 2021). "CCL22 and TRPM5 were not available on the website, so we compared the other four genes’ IHC in normal tissue and tumor tissue." (PMID 33401247, 2020). "In particular, reduced TRPM5 activity leads to an increase in cytosolic Ca2+ concentration, which stimulates proliferative pathways and the production of inflammatory cytokines such as IL-6 and CXCL10, with particularly marked effects at the invasive edges of the tumor." (PMID 40507957, 2025).
infection (7 papers, 2021 to 2025). The state of being infected such as from the introduction of a foreign agent such as serum, vaccine, antigenic substance or organism. "Consistently, infections with NH57388A were more severe in Trpm5–/– mice, with more Trpm5–/– mice dying during the first 3 days of infection, further underlining the importance of BC-dependent bitter signaling in fighting airway infections." (PMID 35503420, 2022). "Moreover, bitter taste signaling in tuft cells as well as ATP release via Panx1 is crucial for infection outcome, since we observed a reduced survival in Trpm5−/− as well as Panx1−/− mice, when compared to Trpm5+/+ animals, and Trpm5−/− mice showed a greater weight loss 48 h post infection." (PMID 39794305, 2025). "This time point had been established as being crucial for survival following infection in our previous infection experiments in which Trpm5−/− mice develop a more severe infection." (PMID 39794305, 2025). "Prior to infection, DCs were treated with tracheal supernatants obtained from denatonium-treated Trpm5+/+ and Trpm5−/− mice." (PMID 39794305, 2025). "The number of recruited DCs in Trpm5−/− as well as in Panx1−/− mice three days after infection was significantly lower compared to those in infected Trpm5+/+ mice." (PMID 39794305, 2025). "Taken together, these results demonstrate that tuft cells play a prominent role in local DC activation at the site of infection, which involves Trpm5 and Panx1 channels but is independent from ACh release from tuft cells." (PMID 39794305, 2025). "In the experiment with the higher inoculum (4.32 × 107), we found higher loads of bacteria in the spleens of Trpm5–/– mice in comparison with controls, indicating a systemic spreading of the infection in Trpm5–/– mice." (PMID 35503420, 2022). "C3 staining in tracheal sections from mice infected with the P. aeruginosa strain NH57388A on day 1 after infection revealed a strong signal in the subepithelial layer in WT tracheae, whereas the signal in Trpm5–/– mice was less pronounced." (PMID 35503420, 2022). "FACS analysis of bronchoalveolar lavage fluid (BALF) cells, tracheal cells, and lung cells collected 4 hours after infection revealed differences between the immune cell populations in WT and Trpm5–/– mice." (PMID 35503420, 2022). "Increased generation of Trp63CreERT2 labeled alveolar epithelium in Trpm5 null mutants following PR8 infection." (PMID 36129169, 2022). "In 3 other experiments with lower infection doses (2.4 × 106 CFU, 4.6 × 106 CFU, and 6.2 × 106 CFU), 11 of 13 control mice survived 3 days after infection, while 8 out of 12 of the Trpm5–/– mice died or had to be euthanized during the first 3 days." (PMID 35503420, 2022). "The increase in IL-1α, IL-6, KC, MCP-1, G-CSF, and eotaxin was abolished in Trpm5–/– mice after infection." (PMID 35503420, 2022). "In WT mouse monocytes, alveolar macrophages and NK cell numbers increased after infection, whereas in Trpm5–/– mice only NK numbers significantly increased." (PMID 35503420, 2022). "The increase in IL-1, IL-6, KC, MCP-1, G-CSF and eotaxin was abolished in TRPM5−/− mice after infection." (PMID 36139480, 2022). "Consistently, infection with P. aeruginosa was more severe in TRPM5−/− mice, with more TRPM5−/− mice dying during the first 3 days of infection." (PMID 36139480, 2022). "Overall, Trpm5–/– mice lost more weight 48 hours after infection compared with controls and exhibited a higher bacterial load 3 days after infection." (PMID 35503420, 2022). "Here, infection with O. ostertagi induced the expression of some Tuft cell markers, including POU2F3, CHAT, TRPM5, and GFI1B in cattle." (PMID 40076885, 2025). "Consistently, TH17 cell counts were increased two days post infection with P. aeruginosa in the lungs of Trpm5+/+, but not of Trpm5−/− mice." (PMID 39794305, 2025).
infection (continued). "The uninfected Gng13-cKO and Trpm5-KO mice displayed significantly more activated caspase 3, 8 or 9-positive cells than uninfected WT mice whereas the infection did not significantly alter the number of activated caspases 3, 8 or 9-positive cells in either the Gng13-cKO or Trpm5-KO proximal colon." (PMID 37954611, 2023). "Furthermore, the concentration of IL-17A, a key cytokine in host protective immunity to infection secreted for example by TH17 cells, was elevated in the plasma of denatonium-treated Trpm5+/+ mice compared to controls but not in plasma of Trpm5−/− mice." (PMID 39794305, 2025).
kidney (1 paper, 2012). "We performed qRT-PCR analyses to investigate mRNA expression of gustducin, TrpM5, NeuroD, SNAP25, and polycystic kidney disease 2-like 1 (PKD2L1)." (PMID 22536412, 2012).
kidney disease (1 paper, 2019). "Proteins related to TRP channels, including TRP-melastatin 5 (TRPM5), polycystic kidney disease-1-like 3 (PKD1L3), and polycystic kidney disease-2-like 1 (PKD2L1), are also expressed in taste cells." (PMID 31040368, 2019).
metabolic disorders (1 paper, 2025). "TRPM4 is involved in arrhythmias and stroke, while TRPM5 dysfunction affects insulin resistance, contributing to metabolic disorders." (PMID 40227837, 2025).
TRPM5 also shares sentences with these, for which no sentence is quoted: alcohol use disorders (1 paper); Anosmia (1); bladder carcinoma (1); breast carcinoma (1); chronic hepatitis C (1); colorectal cancer (1); Insulin resistance (1); intestinal infections (1); liver cirrhosis (1); prostate carcinoma (1); rectal cancer (1); Trichinella spiralis infection (1).